NAALAD2 (N-acetylated alpha-linked acidic dipeptidase 2)
Description:
Has N-acetylated-alpha-linked-acidic dipeptidase (NAALADase) activity. Also exhibits a dipeptidyl-peptidase IV type activity. Inactivates the peptide neurotransmitter N-acetylaspartylglutamate.
Synonyms: GCPIII; NAALADASE2; GCP3; GPCIII
Tractability: Small molecule: a structure with a bound ligand is known; it has a high-quality binding pocket; it belongs to a druggable protein family. Antibody: its Gene Ontology location is reachable by antibodies, with high confidence; UniProt places it where antibodies can reach, with medium confidence; UniProt predicts a signal peptide or a membrane-spanning region. PROTAC: a small molecule that binds it is known.
Target class: Metallo protease M28 family; Enzyme; Protease; Metallo protease; Metallo protease MH clan; Metallo protease M28B subfamily
Gene: Protein-coding gene on chromosome 11 (90,131,515 to 90,192,894, forward strand). Ensembl gene ENSG00000077616.
Subcellular location: Cell membrane
Subcellular location (Human Protein Atlas): Nucleoplasm
Pathways (Reactome):
Metabolism: Aspartate and asparagine metabolism
Gene Ontology:
Molecular function: protein binding; carboxypeptidase activity; dipeptidase activity; dipeptidyl-peptidase activity; serine-type peptidase activity; metallocarboxypeptidase activity; N-formylglutamate deformylase activity; peptidase activity
Biological process: proteolysis
Cellular component: membrane; plasma membrane
Genetic constraint (gnomAD): Loss-of-function variants: 53 observed, 54.12 expected, observed/expected ratio (o/e) 0.98, 90% interval 0.78 to 1.23. The upper end of that interval is the gene's LOEUF score, 1.23, which puts it in group 5 of 6, group 1 being the genes least tolerant of losing a copy. Missense variants: 590 observed, 603.7 expected, observed/expected ratio (o/e) 0.98, 90% interval 0.91 to 1.05. Synonymous variants: 183 observed, 213.4 expected, observed/expected ratio (o/e) 0.86, 90% interval 0.76 to 0.97.
Homologues: Orthologues: chimpanzee NAALAD2 (99% identical), macaque NAALAD2 (96% identical), dog NAALAD2 (90% identical), rabbit NAALAD2 (90% identical), guinea pig NAALAD2 (89% identical), rat Naalad2 (88% identical), mouse Naalad2 (88% identical), pig NAALAD2 (86% identical), zebrafish naalad2 (67% identical), Caenorhabditis elegans gcp-2.1 (33% identical), Caenorhabditis elegans gcp-2.2 (31% identical). Paralogues in human: FOLH1 (69% identical), NAALADL1 (38% identical), TFR2 (25% identical), TFRC (25% identical), NAALADL2 (23% identical).
Diseases named in the same sentence as NAALAD2 in open-access papers:
NAALAD2 is named in the same sentence as 13 diseases in open-access papers, as found by Europe PMC text mining. Sharing a sentence is not in itself a finding about the gene and the disease. The quoted sentences say what the papers report.
prostate carcinoma (6 papers, 2012 to 2025). A carcinoma that arises from epithelial cells of the prostate gland. "NAALAD2 encodes human prostate‐specific membrane antigen (PSM), which is a marker of prostatic carcinomas and is the first shown to possess NAALADase activity." (PMID 33448640, 2020). "These include MMP8, a metallopeptidase that contributes to extracellular matrix remodeling, NAALAD2, a peptidase that hydrolyses N-acetyl-aspartyl glutamate and glutamate and a marker of prostatic carcinomas, and ACVRL1, a receptor for TGF-β family of ligands." (PMID 29608722, 2018). "In fact, Naalad2 belongs to the same gene family as the prostate cancer biomarker, prostate-specific antigen." (PMID 22427916, 2012). "NAALAD2, belonging to the N-acetylated alpha-linked acidic dipeptidase (NAALADase) gene family, encodes the human prostate-specific membrane antigen (PSM), a recognized marker for prostatic carcinomas." (PMID 40069600, 2025).
schizophrenia (2 papers, 2023 to 2025). A major psychotic disorder characterized by abnormalities in the perception or expression of reality. "There is evidence that SULT1C4, NAALAD2, and ADGRV1 participate in neurotransmitter regulation, glutamate dysregulation in schizophrenia, and epilepsy and audiovisual disorders." (PMID 40428414, 2025).
myeloma (1 paper, 2025). "Whole exome sequencing of blood and tissue samples highlighted myeloma overexpressed gene (MYEOV), B melanoma antigen family member (BAGE), and N-acetylated-alpha-linked acidic dipeptidase 2 (NAALAD2) as potential mutated genes related to Zinner syndrome." (PMID 40069600, 2025).
Obesity (1 paper, 2017). Accumulation of substantial excess body fat. "Other hub genes, including CCDC50, ORMDL3, PCCA and NAALAD2, have diverse cellular functions and have not been previously implicated as obesity candidate genes." (PMID 28496128, 2017).
prostate tumors (1 paper, 2026). "Additionally, the TE Promoter Finder 2 (TEProf2) pipeline, which predicts TE gene fusion transcripts, predicted splicing of LTRIS_Mus and exon 7 of Naalad2 resulting in expression of a transcript predicted to encode a truncated protein in NPp53T prostate tumors." (PMID 41508128, 2026).
tumor (2 papers, 2017 to 2021). "Upregulation of NAALAD2 expression has been associated with exacerbation of cancerous lesions and facilitation of tumor invasion." (PMID 29228589, 2017).
neurodevelopmental disorder (1 paper, 2024). A behavioral and cognitive disorder with onset during the developmental period that involves impaired or aberrant development of intellectual, motor, or social functions. "But there is no clear link between NAALAD2 and ASD or any neurodevelopmental disorders." (PMID 38572415, 2024).
NAALAD2 also shares sentences with these, for which no sentence is quoted: cancer (2 papers); brain injury (1); epilepsy (1); hearing loss (1); neuroblastoma (1); osteonecrosis (1).